C1orf216 (chromosome 1 open reading frame 216)
Synonyms: FLJ38984
Tractability: No criterion of Open Targets' tractability assessment is met for any kind of drug.
Gene: Protein-coding gene on chromosome 1 (35,713,875 to 35,718,894, reverse strand). Ensembl gene ENSG00000142686.
Subcellular location (Human Protein Atlas): Cytosol; Nucleoplasm
Gene Ontology:
Molecular function: protein binding
Genetic constraint (gnomAD): Loss-of-function variants: 18 observed, 17.4 expected, observed/expected ratio (o/e) 1.03, 90% interval 0.71 to 1.53. The upper end of that interval is the gene's LOEUF score, 1.53, which puts it in group 6 of 6, group 1 being the genes least tolerant of losing a copy. Missense variants: 271 observed, 312.41 expected, observed/expected ratio (o/e) 0.87, 90% interval 0.79 to 0.96. Synonymous variants: 115 observed, 124.5 expected, observed/expected ratio (o/e) 0.92, 90% interval 0.79 to 1.08.
Homologues: Orthologues: chimpanzee C1H1orf216 (99% identical), macaque C1H1orf216 (96% identical), pig C1orf216 (85% identical), dog C1orf216 (84% identical), rabbit C1orf216 (84% identical), guinea pig C1orf216 (83% identical), mouse 5730409E04Rik (83% identical), rat C5h1orf216 (80% identical), tropical clawed frog c2h1orf216 (47% identical).
Diseases named in the same sentence as C1orf216 in open-access papers:
C1orf216 is named in the same sentence as 2 diseases in open-access papers, as found by Europe PMC text mining. Sharing a sentence is not in itself a finding about the gene and the disease. The quoted sentences say what the papers report.
Hypertension (1 paper, 2021). The presence of chronic increased pressure in the systemic arterial system. "Two genes each from LEAD vs. CVD comparison were found to be linked to hypertension status (GLI4 and MNDA) and usage of statins (FAM167A and C1orf216) as well as 58 genes (54 and 4 from LEAD vs. CVD and AAA vs. CVD comparisons, respectively) were related to acetylsalicylic acid medication." (PMID 33801150, 2021).
tumor (1 paper, 2024). "The outcomes of the Kruskal–Wallis test unveiled a significant correlation between high expression levels of C1orf216 and EEF1E1 (p < 0.05), high expression of SRPRB (p < 0.01), high expression of RABGGTB (p < 0.001), and larger tumor size within the HCC cohort." (PMID 38972883, 2024).